SPACA7 (sperm acrosome associated 7)
Description:
Involved in fertilization. Does not seem to play a direct role in sperm-egg binding or gamete fusion.
Synonyms: C13orf28
Tractability: Antibody: UniProt places it where antibodies can reach, with medium confidence; UniProt predicts a signal peptide or a membrane-spanning region; its Gene Ontology location is reachable by antibodies, with medium confidence.
Gene: Protein-coding gene on chromosome 13 (112,376,355 to 112,434,689, forward strand). Ensembl gene ENSG00000153498.
Subcellular location: Secreted; Cytoplasmic vesicle, secretory vesicle, acrosome; Cytoplasmic vesicle, secretory vesicle, acrosome lumen
Subcellular location (Human Protein Atlas): Acrosome; Microtubules; End piece; Equatorial segment; Mitochondria; Principal piece; Predicted to be secreted
Gene Ontology:
Cellular component: acrosomal vesicle; extracellular region; acrosomal lumen
Genetic constraint (gnomAD): Loss-of-function variants: 12 observed, 12.4 expected, observed/expected ratio (o/e) 0.97, 90% interval 0.62 to 1.55. The upper end of that interval is the gene's LOEUF score, 1.55, which puts it in group 6 of 6, group 1 being the genes least tolerant of losing a copy. Missense variants: 111 observed, 135.29 expected, observed/expected ratio (o/e) 0.82, 90% interval 0.7 to 0.96. Synonymous variants: 53 observed, 51.18 expected, observed/expected ratio (o/e) 1.04, 90% interval 0.83 to 1.3.
Homologues: Orthologues: chimpanzee SPACA7 (95% identical), macaque SPACA7 (84% identical), dog SPACA7 (38% identical), mouse Spaca7 (37% identical), rat Spaca7 (34% identical).